TGM2 (transglutaminase 2)
Diseases named in the same sentence as TGM2 in open-access papers (continued):
Sharing a sentence is not in itself a finding about the gene and the disease.
tumor (232 papers, 2005 to 2026). "Intra-cellular (tumour cell) TGM2 positivity was associated with a better prognosis (HR = 0.74, 95% CI 0.59–0.92) with a larger effect stronger in hormone-receptor-negative cases (HR = 0.56, 95% CI 0.37–0.85)." (PMID 39516660, 2024). "In univariable analysis intra-cellular (tumour cell) TGM2 positivity was associated with a better prognosis (HR = 0.75, 95% CI 0.61–0.92; P = 0.0053)." (PMID 39516660, 2024). "TGM2 is also associated with the recruitment of tumor-associated macrophages, which exaggerates inflammation." (PMID 39115570, 2024). "A strong TGM2 expression was associated with advanced tumor stages and predicted worse prognosis regarding progression-free and overall-survival, even at early stages." (PMID 37443286, 2023). "Strong TGM2 expression was associated with tumor size, lymph node metastasis and distant metastasis." (PMID 37443286, 2023). "TGM2 is a multifunctional protein that plays an important role in the adhesion and migration of cells and is associated with tumor formation." (PMID 37115802, 2023). "DNAJA1 also stabilizes cell division cycle 45 to promote tumor progression, while it binds to transglutaminase 2 associated with cell survival." (PMID 36316326, 2022). "Deficiency in TGM2 resulted in a significant slowdown in tumor initiation and growth over time in vivo." (PMID 34103685, 2021). "The aberrant expression of TGM2 has been demonstrated to be linked with a series of aggressive phenotypes of tumor cells, such as tumor growth, metastasis, epithelial-mesenchymal transition, and cancer stem cell property." (PMID 33637086, 2021). "The association between TGM2 expression and tumor-promoting macrophages was verified by examining human GC tissue samples." (PMID 32467608, 2020). "Our study demonstrated that copy number amplification of TGM2 in GC was highly associated with the recruitment of macrophages into the tumor microenvironment, leading to enhanced tumor-promoting inflammation." (PMID 32467608, 2020). "Gene set enrichment analysis of expression microarray data for GC samples with high or low TGM2 expression showed that increased TGM2 expression was associated with tumor-promoting inflammation in GC." (PMID 32467608, 2020). "Transglutaminase 2 has been implicated in a large variety of cellular functions, many of which are crucial in tumor cell proliferation, survival, and metastatic spread." (PMID 30691081, 2019). "The expression of transglutaminase (TG2), a calcium-dependent protein encoded by the TGM2 gene associated with tumor cell proliferation, metastasis, and drug resistance, is closely linked with constitutive activation of NF-κB." (PMID 29907126, 2018). "Based on the association of TGM2 with the modulation of several genes, additional experiments were performed to evaluate its role in tumor progression." (PMID 30108682, 2018). "The cooperative effect of CDKN1A and TGM2 knockdown indicates that they provide complementary contributions to tumor suppression and that loss of each gene function is critical for oncogenic transformation." (PMID 26956429, 2016). "Studies have shown that TGM2 is also associated with the self-renewal and maintenance of stemness characteristics of tumor stem cells, and could become one of the stemness markers of tumor stem cells." (PMID 39457544, 2024). "Notably, majority targets of TB-2 are implicated in tumor therapy, including TGM2, KIT, EGFR, AURKA, FASN, and CDK2, which have garnered extensive research attention." (PMID 39376614, 2024). "However, our findings clearly indicated that patients with strong TGM2 expression are at risk for tumor relapse." (PMID 37443286, 2023).
tumor (continued). "By contrast, metastatic SKCM showed an increased association compared to the primary one, suggesting that TGM2 might be related to tumor immune infiltration in SKCM and that this association is more pronounced in the metastasis." (PMID 35725560, 2022). "Given a tight association of the mesenchymal subtype and a high degree of tumor necrosis, an enzyme such as transglutaminase 2, or TGM2, was found as a key molecular switch of necrosis-induced mesenchymal differentiation by regulating the master mesenchymal transcription factors." (PMID 33762019, 2021). "Accordingly, it suggested that these 3 downregulated proteins (ANPEP, CAV1, and TGM2) were potentially remained downregulated and might associate with the loss of vascular structures in tumor metastases." (PMID 32756007, 2020). "In this study, we demonstrated that the copy number of the TGM2 gene was amplified in a subset (13.6%) of GC samples and that increased TGM2 expression was associated with tumor-promoting inflammation mediated by recruiting macrophages to the tumor microenvironment." (PMID 32467608, 2020). "They found that higher levels of TGM2 were closely associated with increases in various genes that promote the recruitment and activity of tumor-associated macrophages, malfunctioning white blood cells that drive tumor-promoting inflammation." (PMID 32467608, 2020). "Besides these observations, TGM2 was associated with the modulation of multiple target genes, some of which are involved in tumor progression." (PMID 30108682, 2018). "In particular, TGM2 expression levels were increased in the stroma associated with in situ tumor lesions, suggesting that this gene may act as an early stromal sensor of malignant transformation, also in consideration of the slight decrease in IDC." (PMID 27600076, 2016). "An AGT/TGM2-expressing fibroblast subset is present in both healthy and tumor tissues, suggesting alternative trajectories to the classical NAF-to-CAF transition model." (PMID 42050076, 2026). "Several studies have shown that siRNA-mediated knockdown of tumor-associated genes such as TGM2, EGFR, and MUC1 in solid tumors can effectively reduce tumor proliferation and enhance apoptotic pathways." (PMID 41425727, 2025). "Grouped comparisons confirmed reduced Th1/Th2 cells and an expanded immunosuppressive stroma in TGM2-high tumors, mechanistically linking TGM2 to impaired anti-tumor immunity." (PMID 41050683, 2025). "Studies have demonstrated that inhibiting mitophagy in TGM2-overexpressing cells can reduce cell proliferation and decrease TGM2-induced chemotherapy resistance, revealing a novel role of TGM2-mediated mitophagy in tumor drug resistance." (PMID 41469519, 2025). "TGM2 is minimally expressed in normal epithelial tissues but is upregulated in tumor cells, where it is involved in cell survival, tumor invasion, and motility." (PMID 41463161, 2025). "TGM2, a multifunctional protein, plays key roles in tumor autophagy, metastasis, drug resistance, and pro-tumor inflammation." (PMID 41050683, 2025). "Meanwhile, Immunohistochemistry (IHC) results from mouse tumor tissues showed that the expression of TGM2 was significantly reduced in the sh-TGM2 group compared to the sh-NC group, and increased markedly in the Glu group." (PMID 41469519, 2025). "TGM2 has the roles of promoting cell proliferation, inhibiting apoptosis, and promoting tumor formation." (PMID 41469519, 2025). "In CAFs and tumor stroma, CLIC3 enhances ECM stiffness and angiogenesis in collaboration with the enzyme transglutaminase 2 (TGM2), driving the pro-invasive and pro-angiogenic functions of the tumor microenvironment." (PMID 41465326, 2025). "Concurrently, in a nude mouse model of PDAC established using Gem-R PDAC cells, sh-TGM2 exhibited inhibitory effects on tumor growth and modulated the impact of exogenous Glu." (PMID 41469519, 2025).
tumor (continued). "Given the important role of glutamine (Glu) metabolism in tumor drug resistance, we investigated the role and exact mechanism of transglutaminase type 2 (TGM2) in influencing PDAC sensitivity to gemcitabine." (PMID 41469519, 2025). "Functional and clinical validation has shown that higher TGM2 expression is associated with poorer survival, elevated gemcitabine IC50 values, and increased abundance of tumor-infiltrating macrophages in PDAC patients." (PMID 41469519, 2025). "We carried out TGM2 immunostaining of tissue micro-arrays comprising 2169 tumour cores and scored these for both intra- and extra-cellular and expression." (PMID 39516660, 2024). "On the other hand, tumour progression was increased and survival rate reduced in TGM2 knockout mice compared to wild-type and TGM2 activation induces programmed cell death." (PMID 39516660, 2024). "The fusion protein that binds to Transglutaminase 2 (TGM2) was selectively delivered to targeted tumor sites, significantly improving the antitumor activity and decreasing the systemic toxicity of rmhTNFα." (PMID 39204319, 2024). "Transglutaminase-2 (TG2) plays a crucial role in extracellular matrix (ECM) cross-linking within the tumor microenvironment (TME)." (PMID 38534736, 2024). "Several studies have shown that TGM2 exhibits strong expression and activity in the stromal tissue surrounding tumors, indicating its involvement in tumor aggressiveness." (PMID 38472489, 2024). "A limitation of this study is the use of TGM2 expression derived from a single 0.6 mm core of tumour tissue." (PMID 39516660, 2024). "In CRC, an increased TGM2 mRNA expression in tumor tissue in comparison to normal tissue was reported with an association to a worse overall survival." (PMID 37443286, 2023). "The number of tumors and the tumor volume in the TGM2-OE group were significantly lower than those in the vector control group." (PMID 37115802, 2023). "We confirmed an elevated expression of TGM2 in tumor tissues compared with matched normal colon epithelium and highlighted TGM2 as a potential target for the diagnosis and treatment of CRC." (PMID 37443286, 2023). "The same study revealed that the expression of the lncRNA was tightly correlated with the expression of the TGM2 coding gene in several cell lines and tumor tissues, suggesting its role as a cis acting transcriptional regulatory lncRNA." (PMID 36824360, 2023). "Patients undergoing adjuvant chemotherapy and patients developing tumor relapse showed more frequently a strong TGM2 expression in their primary tumor." (PMID 37443286, 2023). "Previous studies have correlated LncTGM2 and TGM2 expression in tumor tissues and some human cell lines, including lymphoblast (K562), promyeoloblast (HL60) and monocyte (THP-1) cell lines." (PMID 36824360, 2023). "Multivariate analyses identified strong TGM2 expression level as an independent prognostic factor for tumor-related mortality and tumor relapse." (PMID 37443286, 2023). "In contrast, the tumor volume and number of tumors in the TGM2-KO group were significantly higher than those in the WT group." (PMID 37115802, 2023). "MUC16 showed significant co-expression with antigens (tumor-antigens & autoantigens) and acute phase reactants such as transglutaminases (TGM2), CEACAMs, C-Reactive Protein (CRP), and alkaline phosphatase (ALPP)." (PMID 36816942, 2023). "This is the first study, that determined a significant correlation of epithelial TGM2 expression and advanced tumor stages in CRC." (PMID 37443286, 2023). "We profiled TGM2 protein expression in tumor samples of 279 clinically characterized CRC patients using immunohistochemical staining." (PMID 37443286, 2023). "The PCR results showed that the expression level of TGM2 mRNA was significantly higher in MDCK-C09 cells compared with the level in high tumor-forming cells." (PMID 37115802, 2023).
tumor (continued). "To further determine the role of TGM2 in regulating MDCK tumor-formation, we constructed TGM2-KO MDCK cell lines using CRISPR/CAS9 technology and evaluated the effects of TGM2 knockout using real-time PCR and Western blot." (PMID 37115802, 2023). "Recently, TGM2 was reported to affect tumor cell EMT transformation by promoting protein cross-linking and activating stromal fibroblasts." (PMID 37115802, 2023). "On the other hand, the expression of many M2 signature genes—including those for FN1, MARCO, MRC1, MSR1, TGF-β1, and TGM2—decreased with tumor progression." (PMID 37441079, 2023). "Analysis of 279 patients with CRC revealed that TGM2 is expressed in tumor cells in the majority of cases, and that almost 20% of patients show a strong TGM2 expression." (PMID 37443286, 2023). "Another derivative of interest is the arylethynylquinoxaline GK-13, which demonstrated antiproliferative activity by inhibiting tissue transglutaminase 2 (TG2), a ubiquitous calcium-dependent enzyme involved in apoptosis evasion and tumor cell drug resistance." (PMID 35890083, 2022). "TGM2 has been reported to regulate cell cycle protein expression levels in the tumor microenvironment to aid cell cycle progression and facilitate fibroblast proliferation." (PMID 35669563, 2022). "The mRNA levels of INOS, TNF-α, IRF5, IL-10, TGM2, and Arg-1 in the blood of tumor-bearing mice treated with the exosomes were detected by qRT-PCR." (PMID 35600340, 2022). "TGM2 participates in many pathological reactions, including inflammation, chemotaxis of inflammatory factors, tumor progression, wound healing, tissue fibrosis, and immune diseases." (PMID 35669563, 2022). "Given these premises, we sought to investigate the role of TGM2 among all the TGs in SKCM neoplasia in more detail, to better characterize its positive prognostic role in this pathology." (PMID 35725560, 2022). "Tissue transglutaminase 2 (TG2) plays several roles in tumor biology where it is secreted and acts as a crosslinking enzyme capable of stabilizing the fibrillar nature of the extracellular matrix." (PMID 35729402, 2022). "Epigenetic modification at the level of the gene promoter, has also been investigated for years in tumour samples expressing TGM2." (PMID 34449674, 2021). "TGM2 is highly expressed in the non-tumor tissue of HB patients and its expression is decreased 3–7 times in the tumor tissues of the same patients." (PMID 34943977, 2021). "To determine the effect of TGM2 depletion on tumor initiation and progression in vivo, we subcutaneously transplanted SW480 cells with or without TGM2 stably knocked-down into NOD/SCID mice." (PMID 34103685, 2021). "These authors associated host-driven inflammation with upregulation of several proliferative pathways found in tumor cells, including transglutaminase-2 and oncostatin M, a member of the IL-6 family." (PMID 34147126, 2021). "Accordingly, in CRC both a tumor-promoting as well as a tumor-suppressive function of TGM2 have been described." (PMID 34103685, 2021). "This process is controlled via tumor-derived extracellular vesicles, which contain aberrant levels of transglutaminase-2 and fibrillar fibronectin." (PMID 33946672, 2021). "In vivo, tumor initiation and growth were reduced upon genetic knockdown of TGM2 in xenotransplantations." (PMID 34103685, 2021). "In eight investigated pairs, TGM2 was always expressed to a higher extent in the tumor (at least 2-fold, up to 16-fold, P = 0.01) in comparison to the corresponding normal colon epithelium." (PMID 34103685, 2021). "With IHC analysis in our tissue microarray, we also verified that TGM2 was elevated in tumor tissue compared with adjacent normal tissue and had a negative impact on prognosis." (PMID 33637086, 2021).
tumor (continued). "Compared to normal adjacent tissues, tumours showed a 6.04-fold increase in Transglutaminase (TGM2) expression, an enzyme involved in extracellular matrix stiffness, by cross-linking collagen 1 fibres." (PMID 33048956, 2020). "Using ddPCR, we validated the observed amplification of the TGM2 gene in 14 of the 16 patients detected by aCGH (more than or equal to 2.5 copies considering tumor cellularity)." (PMID 32467608, 2020). "Taken together, these data demonstrated that TGM2 expression was highly connected with tumor-promoting inflammation." (PMID 32467608, 2020). "Transglutaminase 2 functions are also related to the dissemination of tumor cells, due also to its role as a cell surface receptor, which can mediate tumor cell–ECM interactions, or modulate tumor angiogenesis." (PMID 30691081, 2019). "In our model, TGM2 showed the highest expression in tumor cells growing in pancreatic tissues, but only 60 and 30% of these levels were detected in PDAC cells growing in liver and lung tissues, respectively." (PMID 30108682, 2018). "The high expression of TGM2 was significantly correlated with the maximum tumor size and a higher tumor-nodule-metastasis stage." (PMID 29785022, 2018). "In these groups several noteworthy changes include the ECM cross-linking proteins, lysyl oxidase, lysyl oxidase-like 1, and tissue transglutaminase II (TGM2), which have been previously shown to play a role in tumor stiffness and progression." (PMID 30154546, 2018). "Fibroblasts expressing TGM2 were observed throughout the tumour stroma, while the expression of PDPN and TNC is lower and more restricted." (PMID 29551776, 2018). "We also investigated TGM2 expression in subcutaneous tumours after injecting HCC cells alone or in conjunction with hepatic stellate cells into nude mice." (PMID 30393774, 2018). "This screen uncovered tissue transglutaminase 2 (TGM2) as a tumor suppressor that inhibits oncogenic transformation of HMECs." (PMID 26956429, 2016). "Consistent with a tumor suppressive role, we found that TGM2 promotes autophagy and prevents an early step of HMEC transformation, the acquisition of anchorage-independent growth." (PMID 26956429, 2016). "More importantly, tumor regression was observed in MCF-7-xenograft tumor-bearing mice treated with both mTORC1 and TGM2 inhibitors compared with those treated with either a single inhibitor or the vehicle control." (PMID 26872016, 2016). "Several studies have shown that tissue transglutaminase, also known as transglutaminase 2, is involved in tumor drug resistance and evasion of apoptosis." (PMID 26872016, 2016). "Further work will be necessary to elucidate other tumor suppressive functions and regulation of TGM2." (PMID 26956429, 2016). "Tissue transglutaminase-2 (TG2), a multifunctional member of the transglutaminase family, has been shown to be critical for tumor initiation and progression." (PMID 26771235, 2016). "Although the role of TGM2 in tumorigenesis is likely context-dependent, our data clearly reveal a tumor suppressive role of TGM2 in a variety of cell lines that represent an early step in transformation and carcinogenesis." (PMID 26956429, 2016). "The exact role of TGM2 in tumor formation is yet to be elucidated but several mechanisms are proposed." (PMID 25247996, 2014).